Y_RNA (Y RNA )
Gene: Miscellaneous RNA gene on chromosome 11 (70,705,167 to 70,705,269, reverse strand). Ensembl gene ENSG00000207196.
Homologues: Orthologues: chimpanzee Y_RNA (99% identical). Paralogues in human: Y_RNA (91% identical), Y_RNA (90% identical), RNY3 (89% identical), Y_RNA (89% identical), RNY3P1 (88% identical), Y_RNA (88% identical), Y_RNA (87% identical), RNY3P5 (86% identical), Y_RNA (86% identical), RNY3P14 (85% identical), Y_RNA (85% identical), Y_RNA (84% identical), and 96 more.